EGFR (epidermal growth factor receptor)
Diseases named in the same sentence as EGFR in open-access papers (continued):
Sharing a sentence is not in itself a finding about the gene and the disease.
glioblastoma (continued). "Amplification or loss of regulation of several other molecular markers in addition to EGFR and PTEN involved in the PI3k pathway have been implicated in human glioblastoma: platelet-derived growth factor receptor (PDGFR), fibroblast growth factor receptor (FGFR), and other tyrosine kinase receptors." (PMID 22479427, 2012). "In a previous MLPA study of 104 glioblastomas, 74 (71%) had additional copies of EGFR." (PMID 22691727, 2012). "Synergistic effects of rapamycin and EGFR TKIs have been observed in several in vitro systems, including glioblastoma multiforme, prostate cancer, pancreatic cancer, squamous cell carcinoma, renal cell carcinoma, leukemia, cervical carcinoma, and NSCLC cell lines, as well as in some xenografts." (PMID 22545054, 2012). "Finally, genetic heterogeneity exists in glioblastoma, including mosaic amplification of receptors such as EGFR, potentially complicating distinctions between neoplastic and non-neoplastic cells." (PMID 22298889, 2012). "Several factors may contribute to this minimal antitumor response to combination therapy of EGFR and mTOR inhibitors in glioblastomas, including mainly therapy resistance or use of inadequate drug doses." (PMID 22530122, 2012). "In addition, human glioblastoma cells efficiently counter the anti-proliferative effects of EGFR inhibitors by continuous activation of the anti-apoptotic PI3K/AKT signaling pathway in vitro." (PMID 23259795, 2012). "In addition, EGFR is dysregulated in the majority of human glioblastomas and EGFR overexpression correlates with shorter survival." (PMID 22295207, 2011). "For example, glioblastoma cell lines presenting EGFR amplification cannot be established." (PMID 21326241, 2011). "Glioblastoma is associated with a number of mutations at the genomic level including mutations in the PTEN tumor suppressor and amplification of the gene encoding the epidermal growth factor receptor (EGFR)." (PMID 21912681, 2011). "However, the role of EGFRvIII as a prognostic or predictive marker of response to EGFR inhibitors in glioblastoma remains controversial." (PMID 21352589, 2011). "Down-regulation of expression of this protein in glioblastoma cell lines resulted in increased proliferation and invasion, decreased apoptosis, and increased EGFR expression, leading to the hypothesis that LRIG is a tumor suppressor." (PMID 21170350, 2010). "Importantly, SNAI2/Slug expression is increased by EGFR activation and promotes a mesenchymal phenotype in glioblastoma cells." (PMID 20565806, 2010). "L2G7 had increased effects in combination with erlotinib in an EGFR mutant glioblastoma model." (PMID 21390244, 2010). "In human U373-MG glioblastoma cells, cannabinoids induce a cell proliferation that is dependent upon the EGFR signalling pathway and in C6 rat glioma cells, expression of the EGFR ligand amphiregulin is an important factor controlling their resistance to the apoptosis produced by cannabinoids." (PMID 20808855, 2010). "Several genes in the central glioblastoma pathways were identified through dramatic copy number alterations, such as amplification of the oncogenes, EGFR, c-MYC, CDK4, PDGFRA, MDM2, and MDM4, and deletion of the tumor suppressor genes, CDKN2A, CDKN2B, and PTEN." (PMID 21113414, 2010). "A recent phosphoproteomic screen for EGFR targets in glioblastoma identified Met." (PMID 19240716, 2009). "Similar observations were made recently in the case of glioblastomas carrying activated EGFR and Met receptors where simultaneous inhibition of EGFR (erlotinib) and Met (SU11274) lead to the downregulation of PI3K pathway, and reduced the size of colony formation in soft agar." (PMID 19240716, 2009).
glioblastoma (continued). "However, both classes of drugs are currently enrolling patients in Phase 2 and Phase 3 trials for the treatment of other EGFR positive cancers, such as cervical, skin, myelogenous leukemia, prostate and glioblastomas (ClinicalTrials.gov, 2007)." (PMID 21892266, 2008). "EGFR activation upregulates genes involved in neural stem cell proliferation: one of these genes is ASPM (abnormal spindle-like microcephaly associated) that promotes neuroblast proliferation and symmetric division and is strongly upregulated in glioblastomas." (PMID 18492260, 2008). "However, glioblastomas expressing the EGFRvIII isoform also frequently express wild-type EGFR transcripts." (PMID 18688287, 2007). "EGFRvIII is found in 67% of tumors with amplified EGFR and reported in 38% of all glioblastomas." (PMID 17437646, 2007). "To further asses the performance of PAC in samples with heterogeneous (wild-type and mutant) transcript expression, we performed PAC on 14 clinical glioblastoma specimens (selected to contain >70% tumor nuclei) that had genomic amplifications of the EGFR oncogene." (PMID 18688287, 2007). "PAC of the EGFR gene in the 14 glioblastomas involved the analysis of 392 exons (434 probe sets)." (PMID 18688287, 2007). "In vitro, an actual antagonistic effect between sequential administration of radiation and 1,3-bis(2-chloroethyl)-1-nitrosourea (BCNU) chemotherapy in primary human glioblastoma cell lines was observed, which was abrogated upon inhibition of EGFR with the a tyrosine kinase inhibitor." (PMID 19384426, 2007). "Furthermore, in human glioblastoma cells, PTEN mutation can cooperate with EGFR activation to increase VEGF mRNA levels by transcriptionally up-regulating the proximal VEGF promoter via the PI3K/Akt pathway." (PMID 19384426, 2007). "In terms of current EGFR therapies, the picture in regards to glioblastomas is mixed." (PMID 17437646, 2007). "Additionally, EGFR-transmitted signals are known to contribute to apoptosis resistance of glioblastoma cells leading, for example, to CDDP insensitivity." (PMID 17342095, 2007). "Indeed, the highly malignant glioblastoma multiforme exhibits EGFR gene amplification at a frequency of 40–50%, with many tumours also exhibiting structural rearrangements of the EGFR." (PMID 15770208, 2005). "Additionally, truncation of the EGFr, which results in deletion of the extracellular domain, is found in a significant proportion of glioblastomas and other tumour types." (PMID 14760366, 2004). "We tested whether the expression of antisense-EGFR RNA had any effect on the ability of glioblastoma cells to form tumours in athymic nude mice." (PMID 11953893, 2002). "Gene amplification and enhanced expression of the epidermal growth factor receptor (EGFR) represent the major molecular genetic alteration in glioblastomas and it may play an essential role in cell growth and in the carcinogenic process." (PMID 10576656, 1999). "Immunostaining of glioblastomas revealed binding in the case with the type III EGFR mutation, the five other specimens without the mutation being negative despite overexpression of EGFR in some cases." (PMID 8645581, 1996). "EGFR, encoding a transmembrane receptor tyrosine kinase acting in the PI3K/AKT/mTOR, MAPK, and other pathways, is among the genes most frequently activated by gene amplification, genetic rearrangements, and single nucleotide variants in IDH-wildtype glioblastomas." (PMID 41546701, 2026). "In glioblastoma diagnostics, genomics is already used to verify whether the tumor is IDH‐ and H3‐wildtype or exhibits other genetic features such as TERT promoter mutation, EGFR gene amplification, or +7/−10 chromosome copy‐number changes." (PMID 40527506, 2026). "Aberrant signaling through insulin-like growth factor 1 receptor (IGF1R) and epidermal growth factor receptor (EGFR) drives glioblastoma (GBM) progression and therapy resistance." (PMID 42200352, 2026).
glioblastoma (continued). "However, the wild-type IDH1/2 contradicts compatibility with a high-grade astrocytoma or oligodendroglioma, and the absence of TERT mutation and EGFR amplification does not align well with glioblastoma." (PMID 41323387, 2025). "However, preclinical data suggest that glioblastoma with EGFR missense mutants may be responsive to EGFR kinase inhibitors." (PMID 40724977, 2025). "Meanwhile, plinabulin might be a potential sensitizer for EGFR-TKI in glioblastoma treatment." (PMID 39877641, 2025). "However, in 2021, the WHO introduced updated classification criteria for gliomas, and IDH wild-type astrocytomas with EGFR amplification, chromosome 7 acquisition with chromosome 10 deletion and TERT promoter mutations are also included in glioblastoma if they have any of the molecular phenotypes." (PMID 39944539, 2025). "Notably, both PDGFRα and EGFR genes are frequently over-amplified in glioblastoma, which may facilitate the virus’s entry into glioblastoma cells." (PMID 41194660, 2025). "Analysis of changes in transcriptomic data of human glioblastoma cell culture after treatment with the aptamer Gol1 revealed profound changes in gene expression; a significant change in gene expression of the key pro-oncogenic signaling pathways mediated by EGFR was shown." (PMID 39940838, 2025). "Furthermore, our analysis suggests that EGFR can serve as an independent prognostic marker for glioblastoma; however, co-expression with the EGFRvIII mutation was not conclusively associated with a poorer prognosis." (PMID 40331985, 2025). "In addition, comprehensive molecular profiling has revealed considerable biological heterogeneity within glioblastoma, with markers such as MGMT promoter methylation, TERT promoter mutations, and epidermal growth factor receptor (EGFR) amplification influencing prognosis and treatment response." (PMID 41523441, 2025). "However, whereas glioblastoma ecDNA primarily carries whole‐gene amplifications (e.g., EGFR), our data reveal that HGSOC eccDNA frequently harbours fragmented regulatory sequences (e.g., promoter‐derived eccMIRs), suggesting tissue‐specific biogenesis mechanisms." (PMID 40984821, 2025). "The OV-Cmab-CCL5 was targeted to EGFR+ glioblastoma (GBM) tumor cells, significantly enhancing the migration and activation of natural killer cells, macrophages, and T cells." (PMID 40295404, 2025). "The presence of an EGFR mutation significantly increased VTE risk in a prospective cohort study of 131 glioblastoma patients (adjusted HR 2.19, 95% CI: 1.15–4.19) but not in a larger retrospective cohort study of 324 glioblastoma patients (HR 1.27, 95% CI: 0.56–2.87)." (PMID 39851266, 2025). "Additionally, an ongoing phase I study investigating bivalent CAR (targeting EGFR and IL13Rα2) engineered T cells recently reported transient reductions of recurrent glioblastoma, which has median overall survival of less than a year, in all treated patients (n=6)." (PMID 40808942, 2025). "OV-Cmab-CCL5 is redirected to EGFR - positive glioblastoma (GBM) cells and facilitates continuous production of the cytokine CCL5 in the tumor microenvironment." (PMID 40697381, 2025). "Moreover, TERTp mutation tended to co‐occur with EGFR, KRAS, and MET in glioblastoma." (PMID 39804195, 2025). "Additionally, lycorine may induce apoptosis in glioblastoma cells through an EGFR-mediated mechanism." (PMID 40286187, 2025). "It is frequently observed that deletions of EGFR ECD occur in glioblastoma (GBM), including EGFRvI, vII, and vIII." (PMID 40859900, 2025). "Epidermal growth factor receptor (EGFR) is frequently dysregulated in glioblastoma (GBM); however, monotherapy with EGFR inhibitors has demonstrated only limited clinical efficacy." (PMID 41195773, 2025). "Therefore, understanding if EGFR is a driver of REP may be helpful to guide therapies and predict patients at high risk for REP in glioblastoma." (PMID 41212363, 2025).
glioblastoma (continued). "EGFR is one of the markers of glioblastoma and may be an effective target protein for aptamers." (PMID 39940838, 2025). "In primary glioblastomas, there is often loss of the INK4A/ARF (cyclin-dependent kinase inhibitor 2A/B—CDKN2A) gene locus, mutations in the phosphatase and tensin homolog deleted on the chromosome 10 (PTEN) gene, and amplification or loss of the epidermal growth factor receptor (EGFR) gene." (PMID 39770078, 2024). "In the 2021 WHO CNS, glioblastoma is defined as a tumor with obligatory wildtype IDH1/2, characterized by diffuse astrocytic histology and at least one of the following features: necrosis, microvascular proliferation, gain of chr 7 and loss of chr 10, EGFR amplification, or TERT mutation." (PMID 39684714, 2024). "Diagnosis of IDH-wild-type glioblastoma within the context of an IDH-wild-type diffuse and astrocytic glioma is dependent on the presence of several criteria—microvascular proliferation, necrosis, TERT promoter mutation, EGFR gene amplification, or +7/−10 chromosome copy number changes." (PMID 38891962, 2024). "Inhibiting HDAC and EGFR signals could be synergistically used to suppress glioblastoma." (PMID 38396993, 2024). "Thus, the presence of any of the following five criteria is sufficient to designate an IDH-wildtype diffuse astrocytic glioma as glioblastoma: microvascular proliferation, necrosis, TERT promotor mutation, EGFR gene amplification, or 17/–10 chromosome copy number changes." (PMID 38553638, 2024). "Mutual exclusivity of NF1 and EGFR alterations in IDH-wildtype glioblastoma was further substantiated using two publicly available resources, TCGA and CPTAC, totaling 368 genomically-characterized glioblastomas after excluding samples with pathogenic IDH1/2 alterations." (PMID 39472976, 2024). "In glioblastoma (GBM), the progression may be associated with alterations in the Wnt, transforming growth factor beta (TGF-β), VEGF, EGFR, cyclin-dependent kinase 2A (CDKN2A), nuclear factor-κB (NF-κB), and phosphatidylinositol-3-kinase (PI3K)/AKT/mammalian target of rapamycin (mTOR) pathways." (PMID 39682237, 2024). "Thus, the sensitivity of glioblastoma cells to reovirus could depend on the signaling status in the EGFR/Ras/MAPK pathway." (PMID 39772250, 2024). "In glioblastoma, EGFR gene amplification is the most common RTK mutation, occurring in approximately 40% of cases, predominantly in primary GBM." (PMID 39767571, 2024). "Aberrant EGFR signaling was identified in several human cancers, most commonly seen in glioblastoma multiforme (GBM) and non-small cell lung cancer (NSCLC)." (PMID 38254905, 2024). "In addition, we identify the main biomarkers, including isocitrate dehydrogenase, epidermal growth factor receptor, and telomerase reverse transcriptase, known as potential immunotherapeutic targets in glioblastoma, as well as the current status of clinical trials." (PMID 38932383, 2024). "Moreover, allopregnanolone has been shown to promote cell proliferation in a human glioblastoma (GB) U87 multiforme cell line and the expression of genes associated with tumor progression, including TGF-β1, epidermal growth factor receptor, vascular endothelial growth factor, and cylin-D1." (PMID 38792602, 2024). "Furthermore, miR-374a-targeted genes exhibited significant association with pathways such as cancer, Ras signaling, MAPK signaling, PI3K-AKT signaling, Glioblastoma signaling, EGFR tyrosine kinase inhibitor resistance, mTOR signaling, miRs in cardiomyocyte hypertrophy, EGF/EGFR signaling and glioma." (PMID 39348350, 2024). "Similarly, in glioblastoma, EGFR/EGFRvIII overexpression increases TF expression." (PMID 38719932, 2024).
glioblastoma (continued). "Notably, amplified wildtype EGFR in glioblastoma also converges to expose this epitope." (PMID 38396993, 2024). "Temozolomide (TMZ) therapy offers minimal clinical benefits in patients with glioblastoma multiforme (GBM) with high EGFR activity, underscoring the need for effective combination therapy." (PMID 37429858, 2023). "The epidermal growth factor receptor (EGFR, also known as HER1) is augmented in some solid tumors and its altered expression or mutation has been described as a tumor growth enhancer in different types of cancer, including ovarian cancer, glioblastoma and hepatocellular carcinoma (HCC)." (PMID 37896202, 2023). "Although the epidermal growth factor receptor (EGFR) is a frequent oncogenic driver in glioblastoma (GBM), efforts to therapeutically target this protein have been largely unsuccessful." (PMID 37324218, 2023). "EGFRvIII is a specific tumor antigen of glioblastoma (GBM), while EGFR is an antigen often overexpressed in glioblastoma but also expressed in normal tissues." (PMID 36765623, 2023). "In addition, glioblastoma-specific small EVs are demonstrated to contain the epidermal growth factor receptor variant III (EGFRvIII), the oncogenic mutant variant of EGFR frequently detected in glioblastoma tumours, which stimulates VEGF production and promotes angiogenesis." (PMID 36830690, 2023). "Therefore, the heterogeneity of glioblastoma is conferred by the plasticity of EGFR amplicons." (PMID 38264122, 2023). "Moreover, hijacking enhancers by forming ecDNA could modulate cell viability by regulating oncogene expression, as demonstrated in the case of EGFR in glioblastoma and MYCN in neuroblastoma." (PMID 37448518, 2023). "Therefore, treatments specifically targeting EGFR and its downstream pathways in glioblastoma cells may have potential therapeutic effects." (PMID 37108310, 2023). "Accordingly, a glioblastoma diagnosis is supposed to require, obviously, a setting of IDH-wildtype diffuse and astrocytic glioma, along with microvascular proliferation or necrosis, TERT promoter mutation, EGFR gene amplification or a gain of chromosome 7 and loss of chromosome 10." (PMID 36765898, 2023). "In another study, iNK cells engineered to express an epidermal growth factor receptor (EGFR)-CAR demonstrated anti-tumor activity in models of glioblastoma multiforme (GBM)." (PMID 37147740, 2023). "As such, the EGFR pathway may be a key mediator of glioblastoma progression." (PMID 36765632, 2023). "In particular, EGFR inhibitors with improved brain partitioning, like buparlisib, might be useful to increase drug delivery into the brain and thus be beneficial in the treatment of glioblastoma patients." (PMID 36973040, 2023). "Thus, it is speculated that a similar effect may be achieved with combined therapy against glioblastoma multiforme since it is known that cells of this malignant tumor manifest changes in the ER and EGFR." (PMID 37687164, 2023). "Targeting the epidermal growth factor receptor (EGFR) is one of the potential ways to treat glioblastoma (GBM)." (PMID 37242743, 2023). "Lastly, the developed AuNP-MB immunoassay platform was verified with extracellular vesicle (EV) detection via immune response by showing the existence of EGFR proteins on glioblastoma multiforme (GBM)-derived EVs (108 particle/mL) spiked in human plasma." (PMID 36234217, 2022). "Studies have verified the amplification of 34 genes encoded in eccDNAs, including EGFR, MYC, cyclin-dependent kinase 4, MET proto-oncogene, MDM2, and platelet-derived growth factor receptor alpha in the interphase and mid-term through FISH in glioblastoma samples." (PMID 35494014, 2022). "A promising target in glioblastoma therapy may be EGFR overexpression." (PMID 35453544, 2022).